MED1 (mediator complex subunit 1)
Diseases named in the same sentence as MED1 in open-access papers (continued):
Sharing a sentence is not in itself a finding about the gene and the disease.
pulmonary hypertension (1 paper, 2024). Increased pressure within the pulmonary circulation due to lung or heart disorder. "Other studies have suggested that decreased MED1 expression levels were present in rodent models of pulmonary hypertension and lung endothelial cells, and overexpression of MED1 attenuated the pulmonary hypertensive phenotype in rodents, thereby promoting homeostasis of lung endothelial cells." (PMID 39069619, 2024). "Additionally, MED1 levels are lower in lung tissue or pulmonary artery endothelial cells in patients with idiopathic pulmonary hypertension and rodents with pulmonary hypertension." (PMID 39069619, 2024).
serous neoplasm (1 paper, 2021).
steatosis (1 paper, 2022). Increased lipid within the cytoplasm of cells. "The transcriptional coactivator of the glucocorticoid receptor MED1/PPARBP is also necessary to induce steatosis." (PMID 35052872, 2022).
triple-negative breast carcinoma (1 paper, 2021). An invasive breast carcinoma which is negative for expression of estrogen receptor (ER), progesterone receptor (PR), and human epidermal growth factor receptor 2 (HER2). "In triple negative breast cancer (TNBC), hyperphosphorylated BRD4 has been shown to bind more strongly to MED1, facilitating bromodomain-independent chromatin localization." (PMID 33712563, 2021).
Type 2 Diabetes (1 paper, 2013). "Development of small molecules that could interfere with the phosphorylation or association of PIMT with Med1 might thus offer us novel therapeutic options to effectively treat Type 2 Diabetes." (PMID 24358311, 2013).
cancer (50 papers, 2010 to 2025). A tumor composed of atypical neoplastic, often pleomorphic cells that invade other tissues. "MED1 acts as an AR coactivator that promotes its engagement with cancer-associated enhancers and super-enhancers, and this activity is increased by MED1 T1457 phosphorylation." (PMID 40163908, 2025). "Many studies have reported that inhibition of Med1 expression increased cancer metastasis and is associated with uPAR gene expression." (PMID 38708315, 2024). "Deregulation of CDK7 and MED1 in cancer has been observed in many studies and linked to aggressive clinicopathological features and worse prognosis." (PMID 35158760, 2022). "Differential expression of MED1, a subunit of the tail module, has also been frequently linked to other cancer types." (PMID 28367434, 2017). "In addition, downregulation and loss of expression of MED1 is reported to promote invasion and metastasis in many cancers." (PMID 33251127, 2020). "Similarly, data from BioMuta database indicates higher mutation rate of MED1 in smoking associated cancers." (PMID 33251127, 2020). "Overall, downregulation of MED1 has been linked to enhanced invasion and tumorigenic phenotype in several cancer entities, which may support our observed association of MED1 with clinicopathological parameters of worse outcome in BCa." (PMID 28367434, 2017). "NCOA2, KDM1A, KDM4A, KDM5B and MED1 are AR coregulators implicated in prostate and other cancers." (PMID 26461474, 2015). "Moreover, MED1 is implicated in the pathogenesis of various cancers, with studies demonstrating its overexpression in breast, liver, prostate cancer, and osteosarcoma, while its downregulation has been observed in colorectal, ovarian cancer, and bladder cancer." (PMID 39343952, 2024). "Although these two drugs operate through distinct mechanisms, they share the common characteristic of targeting MED1 condensates in cancer, offering a therapeutic intervention." (PMID 39757214, 2025). "EPI-001 and THZ1 represent innovative approaches in MED1-dependent therapeutic strategies for androgen-resistant cancer." (PMID 39757214, 2025). "Restoring miR-205 levels in tamoxifen-resistant cancer cells reduced MED1 expression and enhanced tamoxifen sensitivity by disrupting MED1 expression and activation by the HER3-PI3K/Akt-MED1 axis." (PMID 39682180, 2024). "Recent studies have suggested that Med1 protein expression plays a role in tumorigenesis and cancer metastasis." (PMID 38708315, 2024). "Med1 is involved in tumorigenesis and cancer progression through its pleotropic functions in various cellular processes." (PMID 38643189, 2024). "Med1 regulates the transcription of various genes and plays a role in cell growth and cancer metastasis." (PMID 38708315, 2024). "Our study can achieve the functional integration of MMP9 and PD-L1 that influence cancer development through targeting MED1." (PMID 39343952, 2024). "The effects of MED1 on the biological behavior of OSCC cancer cells were assessed both in vitro and in vivo." (PMID 39343952, 2024). "Results from cell scratch assays demonstrated that the increased expression of MMP9 recovered the migration capacity of MED1 knockdown cancer cells." (PMID 39343952, 2024). "The close relationship between tumorigenesis among multiple cancer types and numerous mediator complex subunits including MED1, MED12, MED16, and MED19 has been extensively reported." (PMID 35558516, 2022). "In particular, alterations in the expression of the MED1 subunit have been repeatedly reported in the context of metastatic disease throughout different cancer entities." (PMID 35158760, 2022). "This uncovered both induction of NEAT1_2 splicing and poly(A) read-through similar to HSV-1 and IAV infection in cancer cells upon inhibition or knockdown of CDK7 or the MED1 subunit of the Mediator complex phosphorylated by CDK7." (PMID 36279270, 2022).
cancer (continued). "Our results reveal a novel role of MED1 in Pol II transcription and identify phosphorylated MED1 as a targetable driver of dysregulated Pol II recycling in cancer." (PMID 35394046, 2022). "To date, many studies have demonstrated the role of MED1 in the development of cancer, but there are few studies on the effect of MED1 in cardiovascular disease." (PMID 34853629, 2021). "Further studies reveal critical roles for MED1 in epithelial-mesenchymal transition, cancer stem cell formation, and response to anti-HER2 therapy." (PMID 33691110, 2021). "The silencing of MED1 by the RNA nanoparticles led to tumor inhibition as well as resensitization to tamoxifen, thus decreasing lung metastasis and cancer stem cell content." (PMID 34589275, 2021). "In the classification of Luminal A versus Luminal B, the MED1 gene was related to HER2 (+) status of cancer in tissue microarray analysis." (PMID 30866472, 2019). "To define the contribution of Mediator and Cohesin to the regulation of the cancer transcriptional program, we established the genome-wide occupancy of MED1 (Mediator), SMC1A (Cohesin) and the cohesin loader NIPBL." (PMID 27739523, 2016). "Therefore, taken together, these findings highlight the substantial role MED1 plays in cancer development." (PMID 39343952, 2024). "Taken together, these findings indicate that MED1 may facilitate the migration and invasion of cancer cells in vitro, as well as metastasis in vivo." (PMID 39343952, 2024). "The relationship between BAP1 and Med1 expression may be context-dependent and could differ in other cancer cell lines or types." (PMID 38708315, 2024). "Previous research has suggested that MED1 is involved in cancer initiation and progression." (PMID 39343952, 2024). "Moreover, selective inhibition and knockdown of cyclin-dependent kinase 7 (CDK7) as well as knockdown of its phosphorylation target the MED1 subunit of the Mediator complex induce both NEAT1_2 splicing and read-through transcription in cancer cell lines." (PMID 36279270, 2022). "Moreover, the studies revealed that MED1 overexpression can promote epithelial-to-mesenchymal transition, cancer stem cell formation, and resistance to anti-HER2 therapy of the tumors derived from MED1 overexpressing mice." (PMID 35205279, 2022). "More recently, our studies further support the key in vivo role of MED1 in mediating selective ER functions in pubertal mammary gland development, tumor growth, metastasis, cancer stem cell formation and therapy resistance during mammary tumorigenesis as detailed in the next few sections." (PMID 35800368, 2022). "Within both benign and malignant tumors, MED1 exhibited a relatively homogenous expression pattern." (PMID 31695025, 2019). "An important implication of our results is that reduced levels of MED1, MED4, or MED14 may support specific cancer-associated alterations (e.g., SSX2 expression)." (PMID 31695025, 2019). "For example, altered MED1 protein expression has been reported for several cancer entities." (PMID 27050271, 2016). "The PPI network identified that ESRRG was significantly related to 20 genes, including PPARGC1A, PPARGC1B, MED1, CREBCF and so on, 6 of which were confirmed to be positively correlated with ESRRG expression by the XenaShiny TCGA Association Analysis module for single cancer." (PMID 40356747, 2025).
cancer (continued). "This complex interaction between MED1 expression in tumor cells and the immune response warrants exhaustive investigation, as it could unveil novel therapeutic targets and strategies for enhancing the efficacy of cancer treatments." (PMID 39343952, 2024). "As a transcription factor, MED1 is an important part of mega transcription factor-bound in trans enhancers, which can promote estrogen (E2)-mediated improvements in the transcriptional efficiency of downstream genes through ERα, thus promoting the growth of cancer cells." (PMID 34976005, 2021). "Furthermore, cancer-specific survival was significantly worse in the group of low MED1 expression." (PMID 28367434, 2017). "Although the binding of Med1 and BAP1 involved in the cancer growth or metastasis, mechanisms are still unclear." (PMID 38708315, 2024). "In human cancer cells, BRD4S forms nuclear puncta with liquid-like properties and co-localizes with BRD4L, mediator complex subunit 1 (MED1), and histone H3K27ac." (PMID 37509171, 2023). "By reducing the expression of MED1/17 and MED19, the growth and proliferation of cancer cells were inhibited." (PMID 34649520, 2021). "Our studies further revealed that MED1 overexpression promotes epithelial-to-mesenchymal transition (EMT), cancer stem cell (CSC) formation, and the resistance to anti-HER2 therapy of MMTV-HER2 tumors." (PMID 33691110, 2021). "The ABCC3 (canalicular multispecific organic anion transporter 2) gene, the 3′ partner in the MED1 (mediator complex subunit 1)-ABCC3 fusion, is known to efflux therapeutic compounds resulting in multidrug resistance in cancer cells." (PMID 28851357, 2017). "Transcription factors were ranked based on their percentage of overlap with MED1, SMC1A and NIPBL across the genome of each cancer cell." (PMID 27739523, 2016). "The most significant finding in this study is the divergent mechanism of ARfl and ARv567es in regulating p-MED1 recruitment, driving p-MED1 to the UBE2C locus, and then affecting UBE2C expression and cancer cell growth." (PMID 25481872, 2015). "However, in the future, the results of this study will contribute to various research fields, such as the mechanism of regulating the expression of target genes by the binding of Med1 and BAP1 and the growth and metastasis of cancer by Med1 and BAP1." (PMID 38708315, 2024). "Thus, Med1 and BAP1 can serve as biomarkers for cancer development or metastasis, and targeting agents serve as potential gene therapeutic targets in various cancers." (PMID 38708315, 2024). "Further studies can investigate whether Med1 phosphorylation affects the binding ability of BAP1 protein and the role in cancer cell growth and metastasis capacity." (PMID 38708315, 2024). "In addition, an examination of the interaction between Med1 and BAP1 proteins showed that Med1 and BAP1 proteins are binding and are involved in the development and metastasis of cancer." (PMID 38708315, 2024). "In contrast, downregulation of MED1 was described to promote the metastatic spread of human non-small-cell lung cancer and triggers a tumorigenic phenotype in metastatic melanoma indicating context-specific MED profiles in different cancer entities." (PMID 27050271, 2016). "We found that over-expression of MED1 in mammary glands resulted in a slightly increased number of mammary stem and progenitor cells, but no other phenotypical abnormalities or increase in cancer incidence." (PMID 35800368, 2022). "Also, HLA-A, MED1, NOTCH2 and NOTCH3 are related with cancer prognosis." (PMID 30545040, 2018). "Additionally, proteins that are overexpressed in cancer cells are among the targets of down-regulated miRNAs in different treatment conditions, which includes Wnt3A, PPARα, UCP2, CSF1, and MED1." (PMID 24387052, 2014). "Additionally, by analysing TCGA and GTEx data for MED1 in a large SOC cohort, we found significantly decreased MED1 expression between people without cancer and tumour patients." (PMID 37525498, 2023).
tumor (42 papers, 2011 to 2025). "As a pivotal regulator of transcription, MED1 is implicated in the intricate processes of tumor development." (PMID 39343952, 2024). "THZ1 inhibits tumor growth and reverses the drug resistance phenotype associated with hyperphosphorylated MED1 by blocking androgen receptor/MED1 corecruitment." (PMID 36875159, 2023). "Another intriguing study has revealed an increased frequency of MED1 mutations in the circulating tumor DNA in BC patients following endocrine therapy and anti-HER2 treatments." (PMID 35205279, 2022). "Since MED1 has been described to be associated with metastatic spread repeatedly, this subunit is of high interest in this tumor entity, in which metastases and local invasion are crucial for patient outcome." (PMID 28367434, 2017). "Interestingly, low MED1 expression in the primary tumor was significantly associated with positive lymphonodal status (N1) (p = 0.03) and showed a tendency toward the presence of distant metastases (M1) at the time of diagnosis (p = 0.07)." (PMID 28367434, 2017). "Since levels of the protein p-MED1 (the phosphorylated form of the Mediator Complex Subunit 1) detected within the two cell lines were too low to allow the quantification of any variations caused due to drug treatment, we analyzed this parameter in mouse tumor xenograft tissues using immunobloting." (PMID 28045951, 2017). "We carried out IHC staining and found that MED1 expression was dramatically decreased in tumor samples from treatment groups with Dox or a combination of Tam plus Dox." (PMID 39682180, 2024). "The dual nature of MED1 as both an oncogene and tumor suppressor suggest its potential tissue-specific functions." (PMID 39343952, 2024). "In our study, the suppression of Notch signaling in MED1 knockdown OSCC cells resulted in an increase in CD8+ T cell anti-tumor activity by reducing PD-L1 expression." (PMID 39343952, 2024). "By targeting MED1, our study aims to achieve a dual therapeutic effect: modulating the expression of critical genes and regulating anti-tumor immune cells." (PMID 39343952, 2024). "Initially, we utilized the Oncomine database to conduct a comparative analysis of MED1 transcription levels in diverse tumor tissues and their corresponding normal tissues." (PMID 39343952, 2024). "Targeting MED1 phosphorylation by a highly specific CDK9 inhibitor decreases tumor growth through inhibition of Pol II recycling." (PMID 35394046, 2022). "The interference of MED1 function will stop or delay cell proliferation and thus BC tumor progression and metastases." (PMID 35205279, 2022). "Collectively, these data indicated that lapatinib and JQ1 cooperatively disrupt BRD4 and MED1 chromatin binding at a majority of genomic loci, consistent with their capacity to elicit potent effects on adaptive responses and suppress tumor cell growth." (PMID 33980863, 2021). "TWIST1 protein expression was also assessed in primary tumor samples corresponding to the MED1 and MED6 cell lines." (PMID 33948561, 2021). "High nuclear expression of the TWIST1 transcription factor was observed only in the MED1 primary tumor." (PMID 33948561, 2021). "Taken together, these data support that MED1 overexpression promotes MMTV-HER2 tumor migration, invasion, and the expression of genes involved in EMT and ECM degradation." (PMID 33691110, 2021). "Here, through generation of a MED1 mammary gland-specific overexpression mouse model, we further provided strong evidence that MED1 overexpression can promote HER2-driven tumor onset, growth, metastasis, and resistance to anti-HER2 treatment." (PMID 33691110, 2021). "HMGN2 and MED1 have been previously reported as potential tumor suppressors and are known to play important role in DNA damage response." (PMID 33251127, 2020). "Both HMGN2 and MED1 are reported as potential tumor suppressors and are known to play an important role in DNA damage response." (PMID 33251127, 2020).